DNMT1 (DNA methyltransferase 1)
Diseases named in the same sentence as DNMT1 in open-access papers (continued):
Sharing a sentence is not in itself a finding about the gene and the disease.
lymph node metastasis (9 papers, 2012 to 2024). "Lower levels of FOXO3a, and higher levels of FOXM1, SOX2, or DNMT1 were correlated with shorter survival in the lymph node metastasis positive subgroup." (PMID 31296961, 2020). "The results revealed that the significant prognostic factors were histological grade (P = 0.004), lymph node metastasis (P = 0.004), E-cadherin (P = 0.015) and DNMT1 methylation (P = 0.016)." (PMID 24502362, 2014). "Moreover, high levels of FOXM1, SOX2, and DNMT1 were correlated with high histological grade, advanced clinical stage, and lymph node metastasis." (PMID 31296961, 2020). "However, we found a relationship between DNMT1 expression and prognostic significance with clinical parameters, such as lymph node metastasis, distant metastasis and TNM stage." (PMID 29221215, 2017). "However, DNMT1 overexpression in patients with lymph node metastasis (N2, N1-3) and distant metastasis (M0, M1) showed a long overall survival time (P < 0.05), and those in stage III and stage IV also showed a good outcome for OS (P < 0.05)." (PMID 29221215, 2017). "Majority researches were similar to the results above, whereas some studies verified that patients with lymph node metastasis may increase DNMT1 expression." (PMID 29221215, 2017). "DNMT1 expression was associated with age of the patients, menopause status, and tumor localization, while DNMT3a expression was associated with histological types and serum CA125 levels and DNMT3b expression was associated with lymph node metastasis." (PMID 22768205, 2012). "DNMT1 mRNA expression was significantly correlated with TNM stage, pathological differentiation and lymph node metastasis, which is similar to previous findings reported in the literature." (PMID 23408490, 2013). "DNMT1 mRNA expression was significantly correlated with TNM stage, pathological differentiation and lymph node metastasis." (PMID 23408490, 2013). "DNMT1 mRNA expression was significantly correlated with TNM stage, pathological differentiation and lymph node metastasis (all P<0.05)." (PMID 23408490, 2013). "Here, we show that tumors with regional lymph node metastases (pN+) exhibited decreased expression of DNMT1, 3A and 3B, and TET1 and 3 compared to non-metastatic tumors (pN0), suggesting that metastasis requires a distinct expression profile of DNA methyltransferases/demethylases in solid tumors." (PMID 37367043, 2023). "Positive DNMT1 expression was significantly associated with poor overall survival (the median overall survival time: 11.6 months for positive vs. 8.2 months for negative), a high TNM stage, poor differentiation, lymph node metastasis and serum CEA." (PMID 24423239, 2013).
renal cell carcinoma (9 papers, 2016 to 2024). "In order to determine the functions of DNA methyltransferase in kidney tumorigenesis on the molecular level, we examined the mRNA expression levels of DNMT1, DNMT3A, DNMT3B, and DNMT3B variants in renal cell carcinoma tissue." (PMID 28160561, 2017). "MG98 is a promising human DNMT1 antisense inhibitor that does not require incorporation into DNA since it downregulates DNMT1 expression and cancer cell proliferation by reducing the cellular mRNA concentration in a dose-dependent manner in renal cell carcinoma." (PMID 38225241, 2024).
sarcoma (9 papers, 2009 to 2025). A usually aggressive malignant neoplasm of the soft tissue or bone. "In a mouse model for sarcomas, Dnmt1-deficient mice developed sarcomas at an earlier age." (PMID 20119531, 2009). "In high-grade MPNST, an aggressive sarcoma with poor prognosis and no effective targeted therapy, the targeting of DNMT1 with decitabine or DNMT1-selective catalytic inhibitor GSK3685032 caused the transcriptional activation of ERV retrotransposons and subsequent viral mimicry-mediated cell death." (PMID 39056791, 2024). "In synovial sarcoma, the mRNA expression levels of DNMT1 and DNMT3B were similar to or lower than those in other sarcomas, whereas DNMT3A exhibited higher expression levels." (PMID 40299558, 2025). "Our findings are in agreement with the observation that EZH2 and the DNA methyltransferase DNMT1 interact with each other and co‐operate in silencing genes in U2OS sarcoma cells." (PMID 31468686, 2019).
Anxiety (8 papers, 2014 to 2025). Intense feelings of nervousness, tension, or panic often arise in response to interpersonal stresses. "Hospital Anxiety and Depression Scale-Anxiety scores in the anxiousgroup were also significantly correlated with the expression of the DNAmethyltransferases DNMT1/3A, such that greater anxiety severity was associatedwith more DNA expression." (PMID 29503978, 2017). "Thus, the authors suggested that the overexpression of DNA methyltransferase 1 (DNMT1) in the BLA is responsible for the etiology of anxiety associated with BPA exposure via GABAergic disinhibition." (PMID 40469448, 2025). "Overall, these studies indicate that decreased levels of Dnmt1 underlie the anxiety phenotype." (PMID 35998298, 2023). "Recent studies have reported anxiety-like behaviors in adult mice following prenatal deletion of Dnmt1 from neural stem cells." (PMID 35998298, 2023). "In one study using rat dams fed BPA, newborns showed an increase in Dnmt1 mRNA expression levels in their BLA in tandem with increased anxiety behavior observations." (PMID 35998298, 2023). "In fact, we have found that the local blockade of DNMT1 with 5-aza-CdR in the BLA significantly ameliorated anxiety-like symptoms in PRS mice." (PMID 29471396, 2018). "Due to the high expression of DNMT1 in the BLA, it is possible to analyze the role of DNMT1 in long-lasting anxiety using pharmacological methods." (PMID 29471396, 2018). "Prenatal stress mice developed an anxiety-like phenotype accompanied by a significant increase of DNA methyltransferase 1 and a reduced expression of glutamic acid decarboxylase 67 in the basolateral amygdala." (PMID 29471396, 2018). "Regarding neurobehavior, prenatal, low concentration exposure to bisphenol A affected Dnmt1 and Gad67 expression in rat basolateral amygdala, leading to long term anxiety-like behavior." (PMID 27827847, 2016). "The sex-specific alteration in the expression of CYP19A1 and DNMT1 genes suggests that both hormonal and epigenetic dysregulation could underlie the long-term BPA-induced effect on anxiety-like behavior in the offspring." (PMID 40469448, 2025). "Additionally H67D mutant mice with decreased Dnmt1 expression exhibited lower levels of anxiety in the EPM assay compared with wild-type counterparts." (PMID 35998298, 2023). "This provided a direct relationship between the decreased mRNA levels of GAD67 (repressed by promoter hypermethylation) and overexpressed Dnmt1 (increased methylating activity), as well as underscoring a direct role of prenatal stressors in utero and later observed anxiety phenotypes in offspring." (PMID 35998298, 2023). "In a previous study, Low Novelty-Responding (bLR) rats, bred to exhibit increased anxiety and depressive-like behaviors, displayed decreased mRNA levels of Dnmt1 in the dentate gyrus (DG) and CA3 of the hippocampus, compared with their High Novelty-Responding (bHR) counterparts." (PMID 35998298, 2023). "This study represents the first demonstration that PRS facilitates anxiety-like behaviors and attenuates GABAergic inhibition in the BLA of female mice offspring, which is at least partly via DNMT1-related epigenetic reprogramming of GABAergic system." (PMID 29471396, 2018). "Further analysis to uncover the downstream effects of differential Dnmt1 expression has not yet been conducted with regard to anxiety." (PMID 35998298, 2023).
colorectal tumors (8 papers, 2010 to 2025). "Luteolin also reduces the expression of DNMT1 and HDACs in a dose-dependent manner and downregulates calpain and UHRF1 in colorectal tumor cells, thus promoting apoptosis." (PMID 39858410, 2024). "Human colorectal tumors have lower levels of PPARA mRNA and protein than nontumor tissues and loss of PPAR-α promotes colon carcinogenesis by increasing DNMT1 methyltransferase mediated methylation of p21 and PRMT6 methyltransferase mediated methylation of p27." (PMID 32973493, 2020).
head and neck cancer (8 papers, 2015 to 2024). A primary or metastatic malignant neoplasm affecting the head and neck. "DNMT genes have polymorphic variants in which the heterozygous variant 149C/T of DNMT3B is associated with a risk of head and neck cancer, and the overexpression of DNMT1 has a higher risk of tumor relapse." (PMID 34204259, 2021). "Pancancer analysis confirmed DNMT1 overexpression in various cancer types, including head and neck cancers, indirectly suggesting that DNMT1 is a potential target." (PMID 38755637, 2024). "HPV oncoproteins can modulate DNMT1 expression and activity, and previous studies have reported both gene-specific and global DNA methylation alterations according to HPV status in head and neck cancer." (PMID 34298834, 2021). "Increased DNA methyltransferase 1 (DNMT1) and enhancer of zeste homolog 2 (EZH2) levels, along with increased histone H3 lysine 27 trimethylation (H3K27me3) levels, correlated with decreased levels of PTEN in radioresistant head and neck cancer cells." (PMID 33919657, 2021).
hearing loss (8 papers, 2015 to 2025). "We included a total of 25 studies, 12 performed in patients with concurrent presence of a relevant pathology, 5 conducted in induced hearing loss animal models and 8 which focused on genetic screening of DNMT1 specifically." (PMID 38970134, 2024). "This study suggests that inhibition of DNMT1 ameliorates noise-induced hearing loss and indicates that DNMT1 may be a promising therapeutic target." (PMID 33723744, 2021). "Of note, rare variants in DNMT1 and DNMT3A genes have also been reported in noise-induced hearing loss." (PMID 38970134, 2024). "The largest cohort study (n = 1053) conducted in Chinese adults showed polymorphisms in both DNMT1 and DNMT3A that were implicated in noise-induced hearing loss (NIHL)." (PMID 38970134, 2024). "This study was conducted to explore the effects of DNMT1 and DNMT3A polymorphisms on susceptibility to noise-induced hearing loss (NIHL) in Chinese workers." (PMID 30111769, 2018). "Hearing impairment, which affected nearly 15% of the reported families, was mainly observed in Wolfram syndrome and autosomal dominant hearing impairment caused by WFS1 variants, followed by variants of POLG, OPA1, DNMT1 and SLC25A46." (PMID 39423307, 2025). "Our previous study explored that using Dnmt1 inhibitor RG108, or specific siRNA target Dnmt1, could provide protective function against noise‐induced hearing loss in C57BL/6J mice, indicating a potential therapeutic effect of DNA hypomethylation on hearing impairment." (PMID 35352419, 2022).
Hepatic steatosis (8 papers, 2012 to 2025). Steatosis is a term used to denote lipid accumulation within hepatocytes. "We posit that Dnmt1 deficiency ameliorates HFD‐induced hepatic steatosis, at least in part, via increasing the proportion of the periportal hepatocytes." (PMID 37282749, 2023). "Moreover, a recently study on DNMT1 gene knockout (LD1KO) mice showed that DNMT1 deficiency ameliorated HFD-induced hepatic steatosis in mice." (PMID 40166716, 2025). "In addition, the fat content in the HFD used by Remely's study is slightly different from ours, which may have an impact on the expression of Dnmt1 in the liver, since different HFDs with varied fat contents may cause the variations of hepatic steatosis." (PMID 37282749, 2023). "In the liver, it is previously reported that development of hepatic steatosis was accompanied by changes in Dnmt1 and Dnmt3a expression." (PMID 35745277, 2022). "DNMT1 hypomorphic mice exhibit resistance to alcohol-induced hepatic steatosis compared with the wild-type mice." (PMID 32408171, 2020). "Indeed, we found that inhibiting DNA methylation by genetic deletion of Dnmt1 or Dnmt3a dramatically ameliorates hepatic steatosis in diet‐induced obese mice." (PMID 37282749, 2023). "Liver‐specific deletion of Dnmt1 or 3a increases Klb expression and ameliorates HFD‐induced hepatic steatosis." (PMID 37282749, 2023).
hereditary sensory neuropathy (8 papers, 2015 to 2024). "Previous work found that DNMT1 mutations that cause hereditary sensory neuropathy were due to protein misfolding." (PMID 30165906, 2018). "Inactivating mutations in DNMT1 are associated with hereditary sensory neuropathy and adult-onset dementia." (PMID 27032448, 2016). "Dnmt1 mutations in humans contribute to hereditary sensory neuropathy and autonomic neuropathy." (PMID 27279901, 2016).
Hypertension (8 papers, 2020 to 2025). The presence of chronic increased pressure in the systemic arterial system. "The rs2228611 SNP in DNMT1 is associated with susceptibility to essential hypertension in males." (PMID 37947606, 2023). "Hypertension increases endothelial shear stress in the arterial circulation, which further induces DNMT1-dependent endothelial cell DNA hypermethylation and decreases angiogenesis." (PMID 37947606, 2023). "Hydralazine, an antihypertensive drug for treating essential or severe hypertension, is a DNMT1 inhibitor." (PMID 37372091, 2023). "In addition, prenatal exposure of pregnant women to inflammatory stimuli can cause increased expression of DNMT1 and DNMT3B in the offspring, increased expression of inflammatory cytokines, and increased prevalence of hypertension in the descendant." (PMID 38584203, 2024). "WT rats exposed to SU/Hx/Nx developed hypertension and exhibited increased DNMT activity and Dnmt1 and Dnmt3b expression." (PMID 36372233, 2022). "As a result, the expression of DNA methyltransferases DNMT1, 3 A, and 3B and DNA demethylation enzymes TET1 and 3, after correction for AQP1, increased in patients with hypertension." (PMID 32099032, 2020).
pancreatic ductal adenocarcinoma (8 papers, 2012 to 2025). An infiltrating adenocarcinoma that arises from the epithelial cells of the pancreas. "A schematic diagram illustrating the molecular mechanism by which DNMT1 regulates the CBX7/ERK axis in pancreatic ductal adenocarcinoma." (PMID 40387566, 2025). "Our study provides evidence that DNMT1 significantly contributes to the progression of pancreatic ductal adenocarcinoma (PDAC)." (PMID 40387566, 2025). "For example, DNMT1 was overexpressed in pancreatic ductal adenocarcinoma tissues, with a opposite trend in normal pancreatic tissues and silencing of it demethylated Bax gene promoter, which demonstrated increased mRNA expression." (PMID 40370966, 2025). "In pancreatic ductal adenocarcinoma, CSCs expressed higher DNMT1 levels than non-CSCs, deletion of DNMT1 in CSCs reduced their self-renewal and tumorigenic potential." (PMID 29721170, 2018). "In CFPAC-1 cells, derived from a pancreatic ductal adenocarcinoma liver metastasis of a patient with cystic fibrosis, a borderline significant rhythmicity with a 24 h period was found for the PPARG, DNMT1, and DNMT3B expression patterns, and the time-qualified profiles showed different shapes." (PMID 22966223, 2012).
Parkinson disease (8 papers, 2013 to 2025). A progressive degenerative disorder of the central nervous system characterized by loss of dopamine producing neurons in the substantia nigra and the presence of Lewy bodies in the substantia nigra and locus coeruleus. "Parkinson's disease is characterized by the interaction between α-synuclein and DNA methyltransferase (DNMT1), which catalyzes the transfer of a methyl group to DNA." (PMID 40933952, 2025). "To further explore the significance of identified human DNMT1-dependent genes, we evaluated the recent literature on potential blood biomarkers in Parkinson’s disease (PD) patients." (PMID 32178731, 2020). "Variants within genes associated with Parkinson’s disease (PARK9;ATP13A2), neuronal ceroid lipofuscinosis (NCL;TPP1) and hereditary neuropathy (DNMT1) were also identified." (PMID 27217339, 2016). "The goal of this study was to identify conserved DNMT1-dependent regions and putative non-germline ASMs in the human genome and test the vulnerability of these regions to a neurotoxicant associated with Parkinson’s disease." (PMID 32178731, 2020).
retinoblastoma (8 papers, 2017 to 2025). A malignant tumor that originates in the nuclear layer of the retina. "The study also mentions the connection between BIRC5 (survinin) and DNA methylation in retinoblastoma regulated by Dnmt1, Dnmt3a, and Dnmt3b." (PMID 41150792, 2025). "Similarly, DNA methyltransferase 1 is also known as a methyltransferase to contribute to the pathogenesis of retinoblastoma." (PMID 35013138, 2022). "For instance, numerous studies showed that the presence of many dysregulation CRs (e.g., UHRF1, DNMT1, EZH2, BMI1 and HELLS) might lead to an abnormal epigenetic landscape in retinoblastoma (RB), which might be associated with tumorigenesis and malignant progression." (PMID 36318256, 2023). "In contrast, retinoblastoma cell lines, with low levels of TFF3 expression, exhibited hypermethylation of the TFF3 promoter in a DNA methyltransferase 1 dependent manner." (PMID 29100386, 2017). "Despite the deregulated DNMT1 recruitment during replication, DNA methylation maintenance was not severely affected in Y79 cells, which may suggest that other DNMT family proteins might also be involved in maintenance methylation in retinoblastoma cells although DNMT1 plays a dominant role." (PMID 28467809, 2017). "Overexpression of DNMT1 is associated with hypermethylation of tumor suppressor genes as well as inactivation of other genes and genomic regions that may lead to loss of heterozygosity (LOH) in the other RB1 allele in cases of retinoblastoma when only one of the two alleles was not functional." (PMID 41150792, 2025).
skin cancer (8 papers, 2013 to 2025). "In the same way, it has been shown that grape seed proanthocyanidins, an anti-carcinogenic product, caused a reduced global DNA methylation in skin cancer cells related to a decrease in the level of DNMT1 and an increase in the level of p16INK4A." (PMID 23688286, 2013). "Treatment of skin cancer cells with GSPs decreased the levels of global DNA methylation, 5-methylcytosine, DNA methyltransferase (DNMT) activity, and mRNA and protein levels of DNMT1, DNMT3a, and DNMT3b in treated cells." (PMID 24757666, 2014). "Mice with a ko of G9a in keratinocytes show a drastic reduction of DMBA/TPA induced skin tumors, and keratinocyte-restricted ko DNMT1 strongly decreases keratinocyte stem cells, supporting the suggested mechanism explaining tumor resistance of the N-WASP ko mice." (PMID 31608298, 2019). "Interestingly, DNMT1 itself can bind to G9a/GLP, but also to β-catenin, a crucial transcription factor for keratinocyte stem cells which is required for the formation and maintenance of DMBA/TPA induced skin tumor." (PMID 31608298, 2019).